GDF15 (growth differentiation factor 15)
Diseases named in the same sentence as GDF15 in open-access papers (continued):
Sharing a sentence is not in itself a finding about the gene and the disease.
malaise (4 papers, 2019 to 2023). A feeling of general discomfort or uneasiness, an out-of-sorts feeling. "We then examinedthe impact of central and systemic GRASP administration on both cisplatin-and GDF15-induced malaise in rats." (PMID 37506293, 2023). "As a first step in this direction,we developed a peptide antagonist(GRASP) that blocks signaling at GFRAL and thus attenuates GDF15-and chemotherapy-induced malaise." (PMID 37506293, 2023). "Animal studies have had mixed results; on one hand, it has been shown that GDF15 induces malaise in mice and rats, and emesis in musk shrews." (PMID 33903632, 2021). "Importantly, GRASP administrationattenuates both GDF15- and cisplatin-induced malaise in rats." (PMID 37506293, 2023).
metastatic melanoma (4 papers, 2019 to 2025). A melanoma that has spread from its primary site to another anatomic site. "SFD’s versatility was further demonstrated by surfaceome profiling, confirming enrichment of H7-B3 (CD276), ICAM1, and MIC-1 (GDF-15) in metastatic melanoma EV via Western blot and flow cytometry." (PMID 40805206, 2025). "Previous studies in metastatic melanoma patients treated with ipilimumab have shown that elevated serum GDF-15 levels adversely affect overall survival, suggesting that this association may reflect disease characteristics rather than a direct impact on immunotherapy response." (PMID 39766045, 2024).
muscular dystrophy (4 papers, 2014 to 2025). Muscular dystrophy (MD) refers to a group of more than 30 genetic diseases characterized by progressive weakness and degeneration of the skeletal muscles that control movement. "GDF-15 serum levels were within the normal range (mean 320 pg/mL) in 6 children with muscular dystrophy (DMD n = 3 and Ullrich Congenital Muscular Dystrophy n = 3)." (PMID 24484525, 2014). "From our own research, the following scheme can be proposed: low end CK and high end GDF-15 and CXCL10 levels point toward IBM, high end CK and intermediate GDF-15 and CXCL10 levels point toward IMNM, and high end CK and low end GDF-15 and CXCL10 point toward a muscular dystrophy." (PMID 37007787, 2023).
oral cancers (4 papers, 2017 to 2025). "In accordance with our results, which showed a regulation of GDF15 expression by IR in the GSCs, it was previously published that IR could also induce the expression and secretion of this cytokine in oral carcinoma cells." (PMID 38201456, 2023).
pneumonia (4 papers, 2023 to 2026). An acute, acute and chronic, or chronic inflammation focally or diffusely affecting the lung parenchyma, caused by an infection in one or both of the lungs (by bacteria, viruses, fungi, or mycoplasma.). "Potential mechanisms linking baseline levels of CRP, GDF-15 and MMP-8 to pneumonia risk require further study." (PMID 38105941, 2023). "Three baseline serum protein measurements were associated with pneumonia risk independent of measured clinical factors: growth differentiation factor 15 (SHR 1.32; CI 1.02–1.69), C-reactive protein (SHR 1.16, CI 1.06–1.27) and matrix metallopeptidase 8 (SHR 1.14, CI 1.01–1.30)." (PMID 38105941, 2023). "In addition to observing multiple clinical variables associated with pneumonia, we identified 3 baseline serum protein immunoassay measures (GDF-15, MMP-8 and CRP), after adjusting for clinical variables, that were associated with pneumonia events up to 10 years prior to the pneumonia diagnosis." (PMID 38105941, 2023). "In a model adjusted for clinical variables, baseline GDF-15 (SHR, 1.32; 95% CI, 1.02–1.69), MMP-8 (SHR, 1.14; 95% CI, 1.01–1.30) and CRP (SHR, 1.16; 95% CI, 1.06–1.27) remained significant predictors of pneumonia." (PMID 38105941, 2023). "The patients who developed infectious complications (including pneumonia, anastomotic leakage, and surgical site infection) had statistically higher GDF15 than those who did not (P = 0.024)." (PMID 41016991, 2026). "In addition to CRP, baseline GDF-15 and MMP-8 were also associated with future pneumonia risk independent of clinical comorbidities." (PMID 38105941, 2023).
pulmonary embolism (4 papers, 2015 to 2022). The obstruction of the pulmonary artery or one of its branches by an embolus, sometimes associated with infarction of the lung. "GDF15 is regarded as a prognostic biomarker of pulmonary embolism in patients with cardiovascular diseases." (PMID 36444166, 2022). "Growth Differentiation Factor 15 (GDF15), a member of transforming growth factor-beta superfamily, has been used to predict disease progression in cancer, cardiovascular disease, chronic renal dysfunction, and pulmonary embolism 18-23." (PMID 32669960, 2020).
renal carcinoma (4 papers, 2012 to 2024). A carcinoma arising from the epithelium of the renal parenchyma or the renal pelvis. "We found that GDF15 expression is decreased in renal carcinoma tissue." (PMID 38082448, 2023).
sickle cell disease (4 papers, 2014 to 2025). Sickle cell anemias are chronic hemolytic diseases that may induce three types of acute accidents: severe anemia, severe bacterial infections, and ischemic vasoocclusive accidents (VOA) caused by sickle-shaped red blood cells obstructing small blood vessels and capillaries. "In children with sickle cell disease, both Haemoglobin (Hb) SS and HbSβ° have significantly elevated GDF15 levels." (PMID 40019842, 2025). "Although no data exist on longitudinal changes in GDF15 in children with cancer, children with sickle cell disease (a chronic inflammatory condition) experience elevated GDF15 chronically with acute-on-chronic elevations of GDF15 during times of hemolytic crisis." (PMID 38146512, 2023).
spinal muscular atrophy (4 papers, 2020 to 2025). A motor neuron disease that affect the muscles, and characterized by muscle weakness and atrophy resulting from progressive degeneration and irreversible loss of the anterior horn cells in the spinal cord (i.e., lower motor neurons) and the brain stem nuclei. "Elevated GDF15 is not specific to mitochondrial diseases neither is it a diagnostic biomarker; GDF15 is therefore not acceptable as a diagnostic test for mitochondrial diseases such as spinal muscular atrophy and Duchesne muscular dystrophy." (PMID 34445593, 2021). "In a mouse model of spinal muscular atrophy (SMA), a longitudinal transcriptomic study of vulnerable and resistant motoneuron pools showed that in SMA-resistant ocular motoneurons, gdf15 was highly upregulated." (PMID 37626649, 2023).
testicular cancer (4 papers, 2015 to 2022). A primary or metastatic malignant neoplasm that affects the testis. "The increases in plasma GDF-15 levels in testicular cancer patients during chemotherapy and its association with vWF and hsCRP suggest that GDF-15 is a potentially useful biomarker related to endothelial damage." (PMID 25590623, 2015). "Based on data from the literature we selected GDF-15 for further validation on the protein level in plasma of testicular cancer patient during and after treatment, and related GDF-15 levels to known plasma endothelial damage biomarkers (vWF, hsCRP)." (PMID 25590623, 2015). "Plasma levels of GDF-15 (pg/mL), vWF (%) and hsCRP (mg/L) in testicular cancer patients (n = 41) before, during and after completion of bleomycin- and cisplatin-based chemotherapy." (PMID 25590623, 2015). "Based on the available data we decided to study plasma protein levels of GDF-15 in testicular cancer patients before, during and after treatment with BEP-chemotherapy, and relate changes to levels of known endothelial damage biomarkers." (PMID 25590623, 2015). "Furthermore, we showed that BEP-chemotherapy (Bleomycin; Etoposide; Cisplatin) did indeed affect plasma GDF-15 protein levels in testicular cancer patients and that these levels related to known endothelial damage biomarkers such as vWF and hsCRP." (PMID 25590623, 2015). "However, its role in endothelial damage is supported by the fact that GDF-15 levels correlated with proteins known to reflect chemotherapy-related endothelial damage in testicular cancer patients, vWF and hsCRP." (PMID 25590623, 2015). "Since CPT was originally tested as an anticancer drug, and some platinum-based anticancer drugs such as cisplatin and bleomycin have been shown to induce GDF15 in subjects with testicular cancer, one may deduce that a large number of the anticancer drugs could induce GDF15." (PMID 35202387, 2022). "Although short from significance (p = 0.06), baseline (i.e. before start of chemotherapy) GDF-15 protein levels in testicular cancer patients were not different from healthy age-matched males." (PMID 25590623, 2015).
Thromboembolic Events (4 papers, 2020 to 2025). "This distinction makes GDF-15 particularly promising, as many markers for bleeding also serve as markers for thromboembolism, complicating the differentiation between bleeding and thrombotic risk." (PMID 39967200, 2025). "Mechanisms linking GDF-15 with thromboembolism in AF are unknown." (PMID 31280356, 2020).
thyroid (4 papers, 2018 to 2025). "The association between GDF15 and thyroid disorders is less clear." (PMID 41303556, 2025). "Though the literature addresses the role of GDF-15 in thyroid tumorigenesis and progression, further studies are essential to clearly understand its precise mechanisms in thyroid oncology." (PMID 37905271, 2023). "This study aimed to determine the diagnostic utility of GDF-15 mRNA expression in frozen tissue and fine-needle aspiration (FNA) samples from follicular-patterned thyroid lesions and neoplasms." (PMID 37905271, 2023). "Moreover, whether circulating GDF15 concentrations were altered in other thyroid disorders, such as hypothyroid, toxic thyroid adenoma, pituitary TSH adenoma, and resistance to thyroid hormone (RTH), remains unknown." (PMID 30687235, 2018). "Thyroid disorders are common in the general population and their role on GDF15 levels has not been sufficiently addressed." (PMID 41303556, 2025).
triple-negative breast carcinoma (4 papers, 2017 to 2023). An invasive breast carcinoma which is negative for expression of estrogen receptor (ER), progesterone receptor (PR), and human epidermal growth factor receptor 2 (HER2). "In this presented study, we addresses the anti-tumor effects of diltiazem which inhibits cell motility and EMT through elevating GDF-15 expression in triple-negative breast cancer in vitro and in vivo." (PMID 35963873, 2022). "Further, GDF15 knockdown significantly inhibits invasion of HER2-overexpressing and triple-negative breast cancer cells, supporting further preclinical investigation of GDF15-targeted therapies." (PMID 29212236, 2017).
unstable angina (4 papers, 2014 to 2026). "There are limited studies on correlations of the peripheral and coronary blood levels of GDF-15 and VCAM-1, but a study of stable and unstable angina patients identified significant linear correlations between the serum levels of hsCRP in the left forearm vein and coronary sinus for both groups." (PMID 39830114, 2024). "Higher levels of the inflammation and adhesion molecules hsCRP, GDF-15, VCAM- 1 were found in angina patients with NOCAD than in non-symptomatic controls, but neither the peripheral nor coronary levels of these parameters differed between OCAD and NOCAD patients." (PMID 39830114, 2024).
urothelial carcinoma (4 papers, 2019 to 2025). A malignant neoplasm derived from the transitional epithelium of the urinary tract (urinary bladder, ureter, urethra, or renal pelvis). "The latest clinical studies have confirmed that GDF15 inhibits T cell function and migration, and that the combination of GDF15‐neutralising antibody visugroumab significantly enhances the efficacy of the PD‐1 antibody Nivolumab in non‐squamous non‐small cell lung cancer and urothelial carcinoma." (PMID 40292733, 2025). "Five patients suffered severe gastrointestinal bleeding requiring blood transfusions (GDF-15 levels: 2172 pg/mL, 2255 pg/mL, 2297 pg/mL, 2333 pg/mL, and 8347 pg/mL), and one patient suffered macrohematuria due to urothelial carcinoma, not requiring a blood transfusion (GDF-15 level: 851 pg/mL)." (PMID 35455481, 2022).
uterine sarcomas (4 papers, 2019 to 2024). "Furthermore, based on higher serum levels of GDF-15 found in patients with uterine sarcomas compared with those with leiomyomas, circulating GDF-15 was proposed as novel biomarker to discriminate between the two diseases." (PMID 39283723, 2024). "An especially high GDF-15 median level of 1397 ng/L, compared to the uterine sarcoma group (943 ng/L) and ULM group (647 ng/L), suggests that it may be a useful ULMS marker for preoperative differentiation of benign and malignant uterine lesions." (PMID 35454875, 2022). "Differential diagnosis of uLM and uterine sarcomas could be based on GDF-15, and CA125 serum levels, although their applicability is limited since increased expression of these biomarkers is more typical of high-grade tumors." (PMID 34445194, 2021). "Additionally, GDF-15 may serve as a serum biomarker to distinguish uterine sarcomas from leiomyomas." (PMID 39283723, 2024).
Abdominal obesity (3 papers, 2016 to 2023). Excessive fat around the stomach and abdomen. "In addition to this, GDF-15 was positively correlated with WHR, which was associated with abdominal obesity in our study." (PMID 34394348, 2021).
asthma (3 papers, 2020 to 2025). "The discovery of a novel Notch4-Wnt-GDF15 axis in controlling allergic asthma in mice, and its subsequent validation in patients with severe asthma, undoubtedly offers new therapeutic prospects for restoring pulmonary immune tolerance and maintaining systemic balance." (PMID 40443529, 2025). "Compared with healthy subjects and patients with asthma, patients with COPD show a high GDF15 level in the serum, which is negatively correlated with exercise levels." (PMID 37093513, 2024). "However, when comparing the relationship between age and GDF-15 for each subject group, the slope of GDF-15-Age (39.8) in COPD group was steeper than those in other groups (healthy; 2.9, asthma; 22.7, respectively)." (PMID 32847145, 2020).
bone metastasis (3 papers, 2015 to 2025). Transfer of a neoplasm from its primary site to bones. "In particular, higher levels of circulating GDF15 have been shown to be a biomarker of bone metastasis that can be combined with other biomarkers to more accurately predict incidences of bone metastasis." (PMID 31589613, 2019). "For PCa, MIC-1/GDF15 serum levels are an independent predictor of the presence of cancer and in more advanced disease they predict overall survival and bone metastasis." (PMID 25695521, 2015).
cardiac arrest (3 papers, 2016 to 2025). Cessation of breathing and/or cardiac function. "Higher GDF15 levels were found in post‐cardiac arrest patients compared to healthy and paediatric intensive care controls, and higher GDF15 levels correlated with increased mortality and worse neurologic outcomes." (PMID 40019842, 2025). "While several entities demonstrated elevated GDF15, the highest median GDF15 levels were observed in cardiac arrest 7089 pg/mL (interquartile range 3805–13 306) and mitochondrial diseases 4640 pg/mL (1896–14 064)." (PMID 40019842, 2025). "Here, we explored the value of GDF-15 as an early predictor of neurologic outcome after an out-of-hospital cardiac arrest (OHCA)." (PMID 31624933, 2019). "In resolving immunologic conditions, GDF15 levels return to baseline along with heart function, but in various pathologies such as post‐cardiac arrest and CHD, GDF15 levels above a certain threshold appear to be associated with irreversible, detrimental cardiovascular effects." (PMID 40019842, 2025).
cataract (3 papers, 2011 to 2026). Partial or complete opacity of the crystalline lens of one or both eyes that decreases visual acuity and eventually results in blindness. "This gender difference in the levels of GDF15 was also consistent in the serum samples derived from the cataract subjects." (PMID 35160195, 2022). "A total of 105 POAG and 117 cataract patient derived samples were utilized for the analysis of AH GDF15 levels." (PMID 35160195, 2022). "Interestingly, consistent with previous reports, AH and serum samples from male cataract patients contained significantly higher levels of GDF15 relative to female patients, suggesting a definitive gender difference in GDF15 levels." (PMID 35160195, 2022).
cerebrovascular disease (3 papers, 2022 to 2025). "Sustained elevation of GDF15 has been also linked to poor prognosis and increased mortality in patients with cerebrovascular diseases [1265–1268]." (PMID 40407975, 2025).
cholestasis (3 papers, 2017 to 2022). Impairment of the bile flow caused by obstruction within the liver, or outside the liver in the bile duct system. "The present study showed that the increase in the GDF15 levels was positively correlated with the degree of cholestasis and inflammation in cirrhotic PBC patients." (PMID 33178828, 2020).
colorectal adenocarcinoma (3 papers, 2021 to 2024). The most common type of colorectal carcinoma. "The MondoA dependent relationship between TXNIP and GDF15 in response to oxaliplatin-induced ROS can be used to predict aggression and treatment sensitivity in colorectal adenocarcinoma." (PMID 39103698, 2024). "Here, in colorectal adenocarcinoma (CRC) we identify oxaliplatin-induced Thioredoxin-Interacting Protein (TXNIP), a MondoA-dependent tumor suppressor gene, as a negative regulator of Growth/Differentiation Factor 15 (GDF15)." (PMID 39103698, 2024).
Crohn disease (3 papers, 2019 to 2024). A gastrointestinal disorder characterized by chronic inflammation involving all layers of the intestinal wall, noncaseating granulomas affecting the intestinal wall and regional lymph nodes, and transmural fibrosis. "Our results demonstrated consistently higher GDF-15 levels in patients with both Crohn’s disease and ulcerative colitis compared to the control group, irrespective of the biologic treatment received." (PMID 38668313, 2024).
endometriosis (3 papers, 2024 to 2025). The growth of functional endometrial tissue in anatomic sites outside the uterine body. "The role of elevated levels of GDF-15 in a group of women of childbearing age has previously been investigated both in plasma and in peritoneal fluid samples of patients with endometriosis and PCOS, where the level of this parameter was also elevated." (PMID 39456699, 2024). "Analysis of protein contributions revealed shared predictors across multiple diseases, such as growth differentiation factor 15 (GDF15), as well as unique predictors like PAEP for endometriosis." (PMID 40594723, 2025).
endotoxemia (3 papers, 2021 to 2025). "We did this by examining the HPA response in wild-type and Gdf15-deficient mice (Gdf15−/−) to two different infection-related stimuli: 1) lipopolysaccharide (LPS)-induced endotoxemia and 2) systemic infection with Escherichia coli." (PMID 34187898, 2021). "A previous study using a mouse model of endotoxemia proposed that GDF15-mediated hepatic export of triglycerides was necessary to support the heart during disease." (PMID 39951524, 2025).
gastric adenocarcinoma (3 papers, 2021 to 2023). "We noted that stomach adenocarcinoma (STAD) and uterine corpus endometrial carcinoma (UCEC) presented similar patterns to COAD, wherein tumors expressed high miR-216a expression levels along with high GDF15 expression compared to normal tissue." (PMID 34948431, 2021).